IL18 (interleukin 18)
Diseases named in the same sentence as IL18 in open-access papers (continued):
Sharing a sentence is not in itself a finding about the gene and the disease.
rheumatoid arthritis (continued). "In addition to the virus-specific pathways, 12 proteins were also assigned to the rheumatoid arthritis pathway, 12 to the IL18 (WP 4754) or 6 to the fluid shear stress pathways." (PMID 35145507, 2021). "Furthermore, ERK-1/2 pathway is activated by IL-18bPa, which decreases the biological activity of IL-18 induced by TNF-α in rheumatoid arthritis synovial fibroblasts." (PMID 31661546, 2019). "The NLRP3 inflammasome, plays a critical role in the pathogenesis of rheumatoid arthritis (RA) by activating inflammatory cytokines such as IL1β and IL18." (PMID 39791728, 2024). "Consistently, increased IL-18 in synovial tissue of rheumatoid arthritis (RA) patients was reported in multiple studies." (PMID 37415987, 2023). "Patients with rheumatoid arthritis (RA) have increased levels of interleukin-18 (IL-18) and decreased levels of IL-18 binding protein (IL-18BP) in the serum and synovial fluid (SF) compared to those in patients with osteoarthritis (OA) or in healthy controls." (PMID 34530864, 2021). "Some previous reports demonstrated the importance of the balance between IL-18 and IL-18BP in inflammatory bowel disease, in rheumatoid arthritis, and in systemic lupus erythematosus which may help to understand our finding that plasma level IL-18 correlated well with IL-18BP level in eczema." (PMID 28839348, 2017). "IL-18 also plays an important role in the pathogenesis of other inflammatory diseases such as atopic dermatitis, rheumatoid arthritis (RA), adult-onset Still’s disease, Sjögren’s syndrome, and inflammatory bowel diseases including Crohn’s disease." (PMID 23382928, 2013). "The increased productions of IL-1β and IL-18 induce renal inflammation and diseases, and excessive IL-6 expression promotes the development and progression of chronic inflammatory diseases, such as, cardiovascular diseases, Alzheimer’s disease, rheumatoid arthritis, and CKD." (PMID 23922826, 2013). "Interleukin (IL)-18, an important proinflammatory cytokine, plays a potential pathological role in rheumatoid arthritis (RA) and systemic lupus erythematosus (SLE)." (PMID 23153245, 2012). "The function of interleukin-18 (IL-18) was investigated in pertinent animal models of rodent rheumatoid arthritis (RA) to determine its proinflammatory and monocyte recruitment properties." (PMID 20565717, 2010). "To date, inappropriate IL-18 production has been reported both in chronic inflammatory diseases such as Crohn's disease and rheumatoid arthritis (RA), and in allergic diseases such as bronchial asthma and atopic dermatitis." (PMID 16563174, 2006). "In disorders such as rheumatoid arthritis (RA), osteoarthritis (OA), phlebitis, and IBD, GBP5 activates the NLRP3 inflammasome, thereby increasing IL-1β and IL-18 production, which exacerbates local inflammation (55, 138, –, 140)." (PMID 40788157, 2025). "TL1A and IL-18 can both be induced upon TLR activation and are elevated in the serum of patients with inflammatory pathologies, such as rheumatoid arthritis (RA) and asthma." (PMID 38839915, 2024). "The literature has found that other autoinflammatory/autoimmune diseases including systemic lupus erythematosus (SLE), rheumatoid arthritis (RA), type-1 diabetes mellitus, Crohn’s disease, psoriasis, and graft versus host disease are thought to be mediated by IL-18." (PMID 36457027, 2022). "Among these cytokines, IL-18 is the most promising biomarker of AOSD as its serum level is particularly high in AOSD compared to other inflammatory diseases such as rheumatoid arthritis (RA), ankylosing spondylitis (AS), polymyalgia rheumatica, and sepsis." (PMID 33652679, 2021). "Pro-inflammatory cytokines, like IL-6, IL-8, IL-18 and TNF are involved in the inflammatory process of autoimmune diseases, such as rheumatoid arthritis (RA) and SLE." (PMID 31195707, 2019).
rheumatoid arthritis (continued). "The collagen-induced arthritis mouse model is known as a human rheumatoid arthritis model and is reported to exhibit mRNA increases in TNF-α, IL-1β, IL-6, and IL-18 during the progression of arthritis." (PMID 29389956, 2018). "By using an immunoassay that measures specifically free biologically active IL-18, we were able to show that serum IL-18 levels were not higher in rheumatoid arthritis and psoriatic arthritis patients compared to healthy controls." (PMID 37415987, 2023). "The negative correlation between Erdr1 and IL-18 expression has been shown, and therapeutic effects of Erdr1 on inflammatory diseases such as rheumatoid arthritis (RA), psoriasis, and rosacea have been determined." (PMID 33334006, 2020). "Several studies have indicated that IL-18 may play an important role in the pathophysiology of collagen-induced arthritis (CIA), which is a well-established autoimmune animal model of human rheumatoid arthritis." (PMID 31861496, 2019). "Although unlike in rheumatoid arthritis, that the expression of IL-18BP was decreased, it is observed that both plasma levels of IL-18 and IL-18BP in eczema were increased." (PMID 28839348, 2017). "It has been shown that TL1A (TNF-like cytokine) synergizes with IL-12 plus IL-18 in inducing IFN-γ by CD4+ T cells, and TL1A production by immune complex-stimulated monocytes may be involved in the pathogenesis of rheumatoid arthritis." (PMID 21572994, 2011). "Interestingly, rheumatoid nodules have features of type-1 (Th1) granulomas with abundant expression of type-1 inflammatory cytokines, including interferon-γ (IFN-γ) and IL-18." (PMID 20565717, 2010). "In patients with OA, the immunoexpression levels of TNF-α, IL-1β, IL-7, MMP-1, MMP-2, and MMP-3 were significantly higher in patients with active rheumatoid arthritis (RA), whereas the immunoexpression levels of IL-1, IL-2, IL-4, IL-6, IL-15, IL-18, and MMP-3 were not statistically different." (PMID 40004793, 2025). "Similarly, anti‐TNF‐α treatment downregulates IL‐18 but not IL‐12 in patients with rheumatoid arthritis." (PMID 38481033, 2024). "However, another study found that caspase 1 expression was decreased in patients with rheumatoid arthritis, but the activity of caspase 1 was significantly increased, which only promotes the production of IL-18, not IL-1β." (PMID 31367484, 2019). "We aimed to investigate the expression of pro-inflammatory cytokine genes TNFA, IL6, IL12B, IL23, IL18 and immunoregulatory genes FOXP3, TGFB1, and IL10 in the peripheral blood of patients with rheumatoid arthritis (RA) at messenger ribonucleic acid (mRNA) level." (PMID 38534783, 2024). "Indeed, MAIT cells accumulate in lesions of patients with multiple sclerosis, rheumatoid arthritis, inflammatory bowel diseases, and mycobacterial infection, and the activated status of MAIT cells positively correlated with both the plasma levels of IL-18 and disease activity in ulcerative colitis." (PMID 28288675, 2017).
asthma (86 papers, 2005 to 2025). "The IL-18/IL-18R axis is of particular interest in asthma as genome-wide association and machine learning studies have demonstrated that both IL-18 and IL-18R are linked to asthma, including severe asthma." (PMID 40777291, 2025). "IL-18 levels maintained a significant positive causal relationship with asthma (OR = 1.07, 95% CI [1.03–1.11], P = 0.001, FDR = 0.0518)." (PMID 40191192, 2025). "A recent study involving a pediatric cohort found that NLRP3 polymorphisms (such as rs10925023, rs10754558), along with variants in MAVS and IL-18, were significantly linked to a higher risk of asthma, increased IgE levels, and greater disease severity." (PMID 41318536, 2025). "Recent work identified the association of IL-18 with the pathogenesis of asthma, wherein increased IL-18 expression was found in the serum of patients." (PMID 40191192, 2025). "In our study, we determined that the fungal allergen Alternaria alternata, which is associated with severe asthma, rapidly induces airway IL-18 production." (PMID 40777291, 2025). "in 2023 established a causal relationship between asthma and UC through a two‐step, two‐sample MR study in which IL‐18 was found to contribute to a small extent." (PMID 40568744, 2025). "IL-18/IL-18R loci SNPs are linked to asthma in multiple genome-wide association studies and IL-18 has been shown to promote plasticity in ILC2s." (PMID 40777291, 2025). "The identification of novel therapies targeting IL-18 and the associated inflammasome pathways offer promising avenues for treating severe and refractory asthma, addressing the limitations of current biologics." (PMID 39554494, 2024). "It is important to note that increased IL-18 levels were also found to be associated with severe forms of asthma and chronic obstructive pulmonary disease (COPD) and ARDS." (PMID 38983847, 2024). "From these studies, we observe that IL-18’s role differs between asthma and UC: in asthma, elevated levels of IL-18 are associated with disease activity, while in UC, IL-18 exerts pro-inflammatory effects." (PMID 38162651, 2023). "Specifically, we have observed a certain association between asthma and an increase in IL-18 levels, and this increase in IL-18 is also linked to an elevated risk of UC." (PMID 38162651, 2023). "Studies have found increased expression of IL-18 in the serum of asthma patients, with an association between IL-18 polymorphism and susceptibility to asthma, highlighting its potential importance in asthma treatment." (PMID 38162651, 2023). "Simultaneously, a two-step two-sample MR study conducted through mediation analysis revealed that IL-18 is a potential mediator in the causal relationship between asthma and UC." (PMID 38162651, 2023). "We found that SNP rs549908 in the IL18 gene is associated with total IgE among adult subjects with asthma, selected from the general European population in two independent surveys." (PMID 37373658, 2023). "Genetically predicted asthma was found to be positively associated with IL-18 risk according to the IVW (OR 1.0149, 95% CI 1.006-1.024,P=0.002) and weighted median methods (OR 1.02, 95% CI 1.004-1.030,P=0.009)." (PMID 38162651, 2023). "Previous studies have provided evidence suggesting an association between IL-18 and the pathogenesis of asthma, wherein increased IL-18 expression was found in the serum of patients." (PMID 38162651, 2023). "In summary, our study established a causal relationship between asthma and UC, in which IL-18 contributes to a small extent." (PMID 38162651, 2023). "By employing mediation analysis and the delta method for computation, the results indicate that IL-18 explains 3.9% (mediation proportion: 3.9%, 95% CI, 0.9% - 6.9%) of the increased risk of UC-associated asthma." (PMID 38162651, 2023). "The IL18 gene encodes a pleiotropic pro-inflammatory cytokine that is mainly involved in innate and adaptive immune responses in allergic diseases, such as asthma." (PMID 37373658, 2023).
asthma (continued). "Some scrapes of evidence have indicated a positive association between local and/or circulating IL-18 levels and various types of allergy such as AR, asthma, and atopic dermatitis." (PMID 36032502, 2022). "Previous studies have shown that elevated caspase-1 and IL-1β can be detected in mouse models of asthma, and increased IL-18 can also be detected in the sputum of asthmatic patients and is associated with asthma severity." (PMID 36081945, 2022). "In the OVA-induced asthma mouse model, IL-18-deficient animals had reduced neutrophilic airway inflammation and remodeling." (PMID 35664352, 2022). "In asthma, genome‐wide association studies have shown that interleukin‐18 (IL‐18) receptor 1 gene (IL‐18R1) and sputum IL‐18 are increased during exacerbations." (PMID 34194747, 2021). "Elevated IL-18 levels have been associated with asthma exacerbations and IgE levels in asthma patients, shown to be increased in T1DM patients, and associated with glycated hemoglobin (HbA1c) levels." (PMID 34071190, 2021). "Where asthma and the common cold are directly linked to Interferon-gamma (IFNg), IL-8, IL-2 and IL-5, diarrhea is linked to IL-18." (PMID 32746922, 2020). "They found that children with asthma exhibited a deficient IL-18 response and had more severe pneumonia." (PMID 26751073, 2016). "Elevated levels of plasma IL-18 and tryptase and significant correlation between IL-18 and tryptase in asthma implicated that there are certain relationships between IL-18 and tryptase." (PMID 27069315, 2016). "A cohort study of asthma in the Korean population suggested a possible involvement of IL18 polymorphisms in asthma." (PMID 25238536, 2014). "An IL-18 gene polymorphism was reported to be associated with asthma severity; the rs5744247 variant reflecting both higher transcriptional activity and higher serum IL-18 levels." (PMID 23382928, 2013). "Recent evidence suggests that IL18 and genetic variation in this gene are associated with atopy and asthma." (PMID 16759385, 2006). "IL-18 and IL-18R have long been linked to asthma including severe asthma." (PMID 40777291, 2025). "The role of IL-18 or even an association with lung function in asthma is ill-defined." (PMID 39554494, 2024). "IL-18 may act as a potential mediator in the causal relationship between adult-onset asthma and UC, with a mediation proportion of 3.9% (95% CI, 0.6%–6.9%)." (PMID 38162651, 2023). "Genetic variation in IL-18 has been associated with increased risk of atopy and asthma." (PMID 37372463, 2023). "Collectively, these findings support that the reduction of IL-18 might contribute to the salutary effects of weight loss in asthma." (PMID 35807067, 2022). "The other IL-1 family member, IL-18, is also linked to asthma, but with conflicting effects." (PMID 33378691, 2021). "Meanwhile, a lot of studies suggested that IL-18 was associated with asthma severity." (PMID 30373775, 2019). "In addition, IL-18 may act as a potential mediator in the causal relationship between adult-onset asthma and ulcerative colitis." (PMID 40191192, 2025). "Furthermore, IL-18 polymorphisms have been reported to be associated with susceptibility to asthma, suggesting that IL-18 may be therapeutically relevant to asthma." (PMID 40191192, 2025). "Moreover, the linkage disequilibriumwas observed between the −137 and 105 polymorphisms of the IL-18 gene and the105A allele of the IL-18 gene which may be associated with the pathogenesis of asthma." (PMID 18949051, 2008). "IL‐18 in severe asthma contributes to chronic airway inflammation, airway hyperresponsiveness (AHR), and mucus secretion." (PMID 40568744, 2025). "This has been linked to increased levels of cytokines, such as IL-18, IL-6, TNF-α, leukotrienes, and chemokines, in patients with asthma." (PMID 40770020, 2025). "As a key product of inflammasome activation, IL-18 is consistently elevated in asthma, with particularly high levels observed in neutrophilic and severe phenotypes." (PMID 41394843, 2025).
asthma (continued). "The marked elevation of IL-18 is particularly notable when considering recent work highlighting the role of IL-18 in promoting a pathogenic CD101 + CD274 + eosinophil phenotype associated with the pathogenesis of both eosinophilic esophagitis and asthma." (PMID 41013452, 2025). "Given the potential role of IL-18 in asthma, especially severe asthma, the possibility of targeting IL-18 has been proposed as a therapeutic." (PMID 40777291, 2025). "IL‐6 and IL‐18 play complex roles in both asthma and UC, demonstrating the intricate immune mechanisms involved." (PMID 40568744, 2025). "Additional findings implicate inflammasome‐related cytokines (IL‐1β, IL‐18) in neutrophilic asthma phenotypes, poor asthma control, and corticosteroid resistance in pediatric disease." (PMID 41318536, 2025). "The role of interleukin-18 (IL-18) and inflammasomes in chronic inflammatory airway diseases, such as asthma and chronic obstructive pulmonary disease (COPD), has garnered significant attention in recent years." (PMID 39554494, 2024). "Increased IL-18 and tryptase level in moderate and severe asthma patients compared with healthy subjects with significant correlation (r = 0.908, p < 0.05)." (PMID 39554494, 2024). "We explore the multifaceted role of IL-18 in asthma pathophysiology, including its interactions with other cytokines and contributions to both T2 and non-T2 inflammation." (PMID 39554494, 2024). "This has highlighted IL-18 and related proteins as potential therapeutic targets for severe asthma beyond conventional T2 targets." (PMID 39554494, 2024). "It has also been shown that the expression of IL-18BP in the blood of asthma patients is 13 times higher than that of IL-18, suggesting excessive inhibition of IL-18 by IL-18BP in asthma." (PMID 38727246, 2024). "A recent study demonstrated that IL-18 can transdifferentiate innate lymphoid group 2 cell to atypically express ckit ligand and IL-17, particularly relevant in severe asthma patients with recurrent infections." (PMID 39554494, 2024). "Neutrophilic asthma patients showed a marked increase in caspase-4 expression and elevated production of IL-1β and IL-18." (PMID 39795884, 2024). "Ongoing investigations in IL-18 and inflammasomes have revealed their critical roles in the pathophysiology of asthma, particularly in severe forms of the disease." (PMID 39554494, 2024). "We also discuss the role of IL-18 in asthma pathophysiology, autoimmunity, interaction with other cytokines, and its clinical perspective, including the potential therapeutic targets." (PMID 39554494, 2024). "Significantly higher levels of IL-18 were reported in the serum of asthma patients during exacerbations compared to the stable state." (PMID 39554494, 2024). "In this review we have highlighted the multifaceted involvement of IL-18 in asthma, from its interactions with other cytokines to its activation through inflammasome pathways, particularly NLRP3." (PMID 39554494, 2024). "We demonstrated that N-GSDMD, IL-18, and IL-1β were significantly increased in samples with mild asthma compared with those from the controls." (PMID 38849380, 2024). "By synthesizing recent advancements and ongoing research, this review underscores the importance of IL-18 as a potential novel therapeutic target in the treatment of severe asthma and other related conditions." (PMID 39554494, 2024). "These interactions underscore the paradigm shift from a response to an adaptive Th2 response in asthma orchestrated by IL-18." (PMID 39554494, 2024). "It is possible that in the development of asthma, the IL-1β and IL-18 secreted from eosinophils that undergo pyroptosis help drive the progression of airway hypersensitivity and inflammation." (PMID 39611173, 2024). "Recent research has increasingly focused on the role of IL-18 and inflammasomes in a variety of autoimmune and inflammatory diseases, including chronic lung diseases such as asthma and COPD." (PMID 39554494, 2024).